WDR72 (WD repeat domain 72)
Description:
Plays a major role in formation of tooth enamel. Specifically required during the maturation phase of amelogenesis for normal formation of the enamel matrix and clearance of enamel proteins. May be involved in localization of the calcium transporter SLC24A4 to the ameloblast cell membrane.
Synonyms: FLJ38736; AI2A3
Tractability: No criterion of Open Targets' tractability assessment is met for any kind of drug.
Gene: Protein-coding gene on chromosome 15 (53,513,741 to 53,762,878, reverse strand). Ensembl gene ENSG00000166415.
Subcellular location: Cytoplasmic vesicle
Subcellular location (Human Protein Atlas): Vesicles
Gene Ontology:
Biological process: protein localization to plasma membrane
Cellular component: cytoplasm; cytoplasmic vesicle
Genetic constraint (gnomAD): Loss-of-function variants: 109 observed, 117.34 expected, observed/expected ratio (o/e) 0.93, 90% interval 0.79 to 1.09. The upper end of that interval is the gene's LOEUF score, 1.09, which puts it in group 4 of 6, group 1 being the genes least tolerant of losing a copy. Missense variants: 1,328 observed, 1,297.1 expected, observed/expected ratio (o/e) 1.02, 90% interval 0.98 to 1.07. Synonymous variants: 444 observed, 455.33 expected, observed/expected ratio (o/e) 0.98, 90% interval 0.9 to 1.05.
Gene-disease validity (ClinGen):
ClinGen rates the evidence that WDR72 causes each of these diseases.
amelogenesis imperfecta (autosomal recessive): Definitive. Amelogenesis imperfecta (AI) represents a group of developmental conditions affecting the structure and clinical appearance of the enamel of all or nearly all the teeth in a more or less equal manner, and which may be associated with morphologic or biochemical changes elsewhere in the body.
Homologues: Orthologues: chimpanzee WDR72 (99% identical), macaque WDR72 (96% identical), pig WDR72 (85% identical), dog WDR72 (85% identical), rabbit WDR72 (83% identical), mouse Wdr72 (79% identical), rat Wdr72 (79% identical), guinea pig WDR72 (67% identical), tropical clawed frog wdr72 (51% identical). Paralogues in human: VPS8 (18% identical), RBBP5 (8% identical).
Diseases named in the same sentence as WDR72 in open-access papers:
WDR72 is named in the same sentence as 41 diseases in open-access papers, as found by Europe PMC text mining. Sharing a sentence is not in itself a finding about the gene and the disease. The quoted sentences say what the papers report.
amelogenesis imperfecta (9 papers, 2021 to 2026). "WDR72, that is WD repeat-containing protein 72, mutation of which is usually correlated with occurrence of amelogenesis imperfecta." (PMID 38048211, 2023). "Mutations in WDR72 have been previously identified as the cause of amelogenesis imperfecta (AI), a hereditary disease that affect tooth enamel formation." (PMID 35910217, 2022). "One such gene, tryptophan‐aspartate repeat domain 72 (WDR72), has been found to cause a tooth enamel defect when deleted or mutated, resulting in a condition called amelogenesis imperfecta." (PMID 35181734, 2022). "This approach has allowed to establish ATP6V1C2 as a novel recessive dRTA gene in humans and has confirmed the phenotypic expansion of recessive WDR72 mutations from isolated amelogenesis imperfecta to syndromic amelogenesis imperfecta with dRTA." (PMID 33770395, 2021). "Mutations in AMELX, DLX3, LAMA3, LAMB3, and WDR72 were reported in both non-syndromic and syndromic amelogenesis imperfecta." (PMID 33672174, 2021). "WD repeat-containing protein (WDR72) has been considered a cancer suppressor and a potential therapeutic target in renal cell carcinoma, lung cancer and amelogenesis imperfecta." (PMID 38287425, 2024). "It is of our particular future interest to further investigate the role of post-translationally modified WDR72 protein and its molecular function in both healthy enamel tissues and Amelogenesis Imperfecta." (PMID 35301423, 2022). "Seven of the amelogenesis imperfecta-associated genes (CYP27B1, EPNN1, PHEX, SLC4A1, SLC4A4, VDR, and WDR72) are known to cause rickets when mutated." (PMID 33672174, 2021).
distal renal tubular acidosis (8 papers, 2021 to 2026). A kidney disorder of impaired net acid secretion by the distal tubule characterized by hyperchloremic metabolic acidosis. "It was recently associated to distal renal tubular acidosis and this finding rapidly confirmed in 2019 that isolated WDR72 associated hypomature AI was in fact a possible syndromic condition." (PMID 37228816, 2023). "When WDR72 was linked to distal renal tubular acidosis, it helped localize a different transporter in the kidney, which is thought to be a V-type proton ATPase." (PMID 36836560, 2023). "Recessive WDR72 mutations were identified in distal renal tubular acidosis families, and serum acidosis was also confirmed in some AI patients with WDR72 mutations." (PMID 36836560, 2023). "WDR72 has also been identified as causative for distal renal tubular acidosis, which in turn is associated with nephrocalcinosis and thus shares important parallels with FAM20A." (PMID 34957696, 2021). "Mutations in WDR72 are associated with a syndrome characterized by amelogenesis imperfecta and distal renal tubular acidosis (DRTA)." (PMID 34249946, 2021). "Amelogenesis imperfecta IIA3, caused by mutations in the tryptophan-aspartate repeat domain 72 (WDR72) gene, has recently been linked to distal renal tubular acidosis (dRTA)." (PMID 40809612, 2025). "WDR72 is also causative of hereditary distal renal tubular acidosis (dRTA), a rare genetic disease, in an autosomal recessive manner." (PMID 38858654, 2024). "Our findings in WDR72 expression suggest a molecular connection between ectoderm-derived ameloblasts and kidney epithelial cells, supporting the recent reports that WDR72 mutations are associated with distal renal tubular acidosis and Amelogenesis Imperfecta25–28." (PMID 35301423, 2022). "WDR72 has recently been confirmed as regulating vesicle trafficking in ameloblasts and being involved in distal renal tubular acidosis." (PMID 37228816, 2023).
lung carcinoma (8 papers, 2020 to 2025). "In this study, we investigate WD repeat-containing protein 72 (WDR72) on lung cancer cell stemness and explore its underlying mechanism." (PMID 36385964, 2022). "It has been reported that the activation of the AKT/HIF-1α signaling pathway by WDR72 can lead to an increase in the stem-like properties of lung cancer stem cells." (PMID 39268080, 2024). "The significance of our study is that WDR72 can be used as a potential indicator of lung cancer prognosis." (PMID 37197572, 2023). "Recent findings suggested a role for WDR72 in vesicular Golgi transport and unexpectedly in the enhancement of the stemness of lung cancer cells." (PMID 36836560, 2023). "Subsequently, we compared the WDR72 levels between lung cancer cells (LSCs) and LCSCs which were isolated from LSCs." (PMID 36385964, 2022). "WDR72 has been sparsely studied in tumors, thus there is a large space for exploration, and our results demonstrate that WDR72 is overexpressed in lung cancer tissues." (PMID 36385964, 2022). "Application of PI3K/AKT pathway inhibitor LY29004 was able to counteract the influence of WDR72 upregulation on stemness, metastasis, apoptosis, and proliferative gene expression in lung cancer stem cells." (PMID 36385964, 2022). "Application of PI3K/AKT pathway inhibitor LY29004 was able to counteract the impacts of WDR72 upregulation on genes related to stemness, growth, migration, and apoptosis in lung cancer stem cells." (PMID 36385964, 2022). "The promotion of WDR72 overexpression on lung cancer stem cell proliferation and metastasis was also eliminated by LY29004 treatment." (PMID 36385964, 2022). "WDR72 activates the AKT/HIF-1α signaling pathway to enhance the stemness of lung cancer stem cells and promote the growth and metastasis of lung cancer." (PMID 36385964, 2022). "To elucidate the role of WDR72 on the development of lung cancer stemness, we detected the expression of WDR72 in lung cancer stem cells (LCSCs)." (PMID 36385964, 2022). "Overall, our results demonstrate that WDR72 is overexpressed in lung cancer tissues and LCSCs, and that inhibition of WDR72 deters the stemness and protumorigenic effects of LCSCs." (PMID 36385964, 2022). "WDR72 expression was investigated in lung cancer tissues and lung cancer stem cells by Western blot and RT-qPCR." (PMID 36385964, 2022). "The results clued that WDR72 inhibition was responsible for the restraint of lung cancer stem cell growth and metastasis." (PMID 36385964, 2022). "It is speculated that WDR72 may affect non-small-cells through the ferroptosis pathway of lung cancer progression." (PMID 37197572, 2023). "Similarly, compared with normal cells, the expression of WDR72 was significantly elevated in lung cancer cells, and further elevated in LCSCs, suggesting that WDR72 is involved in the regulation of lung cancer cell stemness." (PMID 36385964, 2022). "Up-regulation of WDR72 was found in lung cancer tissues and lung cancer stem cells." (PMID 36385964, 2022). "The expression of WDR72 was further examined in lung cancer patients." (PMID 36385964, 2022). "Therefore, the goal of this study is to investigate the influence of WDR72 on the stemness of lung cancer cells and provide a new treatment strategy for lung cancer." (PMID 36385964, 2022). "The study demonstrated that WDR72 is overexpressed in lung cancer, particularly in LCSCs." (PMID 36385964, 2022). "In comparison to BEAS-2B, WDR72 showed a striking elevation in all the lung cancer cell lines." (PMID 36385964, 2022). "We next evaluated whether WDR72 knockdown could also inhibit the metastasis of lung cancer stem cells." (PMID 36385964, 2022). "Thus, we studied whether WDR72 affected the stemness of lung cancer cells relying on the AKT/HIF-1α pathway." (PMID 36385964, 2022). "In addition, knockdown of WDR72 can inhibit tumorigenesis of lung cancer stem cells." (PMID 36385964, 2022).
lung carcinoma (continued). "Then the level of WDR72 was detected in normal lung epithelial cell line BEAS-2B, and lung cancer cell lines A549, SPCA-1, NCI-H270, PC-9, and H1975." (PMID 36385964, 2022). "Taken together, WDR72 can regulate the AKT/HIF-1α signaling pathway to enhance the stemness of LCSCs and promote the growth and metastasis of lung cancer, but its application in clinical diagnosis and treatment needs to be researched further." (PMID 36385964, 2022). "WDR72 has been recognized as a prognostic biomarker in non-small cell lung cancer, where it modulates the AKT/HIF-1α signaling pathway, contributing to enhanced lung cancer stemness." (PMID 41332473, 2025). "Notably, PEPT7 and PEPT8 originated from a non-coding transcript of WDR72, and non-canonical pMHCs derived from WDR72 have been recurrently observed in glioblastoma, melanoma, and lung cancer samples in IEAtlas-cancer, highlighting their potential as shared TAAs." (PMID 41437377, 2025). "Besides, the changes in caspase-3 activity also indicated that overexpression of WDR72 could not promote lung cancer stem cell apoptosis after inhibiting the AKT/HIF-1α pathway by LY29004." (PMID 36385964, 2022).
nephrocalcinosis (5 papers, 2021 to 2026). Nephrocalcinosis is a disorder that occurs when too much calcium is deposited in the kidneys. "For example, mutations in six of the amelogenesis imperfecta-associated genes (CLDN16, CLDN19, FAM20A, KCNJ1, SLC4A1, and WDR72) are associated with nephrocalcinosis, hypercalciuria, and renal failure." (PMID 33672174, 2021). "Additionally, alterations in the WDR72 gene have been associated with AI occurring alongside renal tubular acidosis and nephrocalcinosis." (PMID 41427162, 2025).
nephrolithiasis (4 papers, 2022 to 2025). The presence of a calculus in the pelvis of the kidney; this is most often composed of mineral salts and proteins. "WDR72-rs551225A (R2 = 0.747 with rs72747347) was associated with low urine pH (Beta: -0.03; CI95%: -0.03-(-0.02); P = 2.6E-15) and increased risk of kidney stones in a set of 150,274 Icelanders (OR:1.09; CI95%: 1.06–1.12; P = 4.8E-08)." (PMID 38858654, 2024). "A recent meta-analysis identified 20 nephrolithiasis-associated loci, including CYP24A1, DGKD, DGKH, WDR72, GPIC1, and BCR locus which were predicted to affect vitamin D metabolism and calcium-sensing receptor signaling respectively." (PMID 35439979, 2022). "Our results elucidated the significance of genetic variation at WDR72, DGKH, CLDN14, SLC34A1, and HIBADH in Chinese patients with nephrolithiasis." (PMID 35910217, 2022).
bladder cancer (3 papers, 2023 to 2025). "WDR72 was identified to have a higher gene expression in the group with recurrence compared to the group without recurrence in bladder cancer." (PMID 38048211, 2023).
colorectal cancer (3 papers, 2023 to 2025). A primary or metastatic malignant neoplasm that affects the colon or rectum. "In addition, we conducted independent IHC experiments for three genes—EPOP, WDR72, and SHH—which have rarely been validated by immunohistochemistry in previous studies of colorectal cancer." (PMID 41425595, 2025). "MeRIP-seq and RNA-sequencing revealed four genes, WD- repeat domain 72 (WDR72), spectrin beta, non-erythrocytic 2 (SPTBN2), microrchidia 2 (MORC2), and prostate androgen-regulated mucin-like protein 1 (PARM1), which could predict the prognosis of patients with colorectal cancers." (PMID 36835633, 2023).
renal cell carcinoma (3 papers, 2022 to 2025). "WDR72, which encodes proteins that facilitate the formation of multiprotein complexes, has also been identified as a potential therapeutic target and prognostic marker in renal cell carcinoma." (PMID 41332473, 2025). "Elevated WDR72 expression has been shown to inhibit cell proliferation and invasion in renal cell carcinoma, supporting its role as a tumor suppressor." (PMID 41332473, 2025). "WDR72 is a tumor suppressor that has the potential to treat renal cell carcinoma, and low expression of WDR72 suggested shortened survival of patients." (PMID 36385964, 2022).
colon cancer (2 papers, 2023 to 2025). "In summary, WDR72 may serve as a novel therapeutic target for colon cancer (CC) in the future; however, its functional role and related pathways in CRC remain to be validated through further in vivo and in vitro experiments." (PMID 41425595, 2025).
non-small cell lung carcinoma (2 papers, 2023 to 2025). A group of at least three distinct histological types of lung cancer, including non-small cell squamous cell carcinoma, adenocarcinoma, and large cell carcinoma. "Despite evidence supporting a basic role of WDR72 in the tumorigenesis of particular cancers, the value of WDR72 in non-small-cell lung cancer (NSCLC), the tumor with the highest mortality rate globally, is undocumented." (PMID 37197572, 2023).
periodontitis (2 papers, 2023 to 2024). An acute or chronic inflammatory process that affects the tissues that surround and support the teeth. "Xu et al32 also described the regulatory role of the XIST/USF2/WDR72 axis in the development of periodontitis." (PMID 39105315, 2024). "The strongest genome-wide signals detected for periodontitis severity were at six closely associated loci within chromosome 15 downstream of the lincRNA RP11-209E8.1 and upstream of the WDR72 gene (p < 0.0001)." (PMID 38068972, 2023).
scrub typhus (2 papers, 2021 to 2023). Scrub typhus is a rare dust mite-borne infectious disease caused by the Orientia tsutsugamushi bacterium and characterized clinically by an eruptive fever which is potentially serious. "Rs2059950 of the DTW domain containing 2 (DTWD2) gene and rs74744256 of the one cut homeobox 1 (ONECUT1) and WD repeat domain 72 (WDR72) gene also showed a significant association of scrub typhus with p < 1 × 10−5." (PMID 33807835, 2021).
type 2 diabetes (2 papers, 2011 to 2024). "We genotyped 1,486 subjects with type 2 diabetes from a Norwegian population-based cohort (HUNT2) for single-nucleotide polymorphisms (SNPs) located near the BNC2, SORCS1, GSC and WDR72 loci." (PMID 21294870, 2011). "In 490 unrelated Emirati nationals with type 2 diabetes mellitus (T2DM), variants in WDR72 showed a trend to association with SCr (rs1031755) or eGFRCrea (rs4776168 and rs10518733), but it was not significant after correction for multiple comparisons (R2 < 0.2 with rs72747347)." (PMID 38858654, 2024).
Calcium nephrolithiasis (1 paper, 2022). The presence of calcium-containing calculi (stones) in the kidneys. "rs578595 at WDR72 was significantly associated with calcium nephrolithiasis in Chinese Han population (p < 0.001, OR = 0.617)." (PMID 35910217, 2022). "Since polymorphisms of WDR72, DGKH, and CLDN14 are predicted to influence in CaSR signaling, our results emphasized the role of abnormal calcium homeostasis in calcium nephrolithiasis." (PMID 35910217, 2022). "Our results indicated that rs578595 at WDR72, rs1037271 at DGKH, rs12654812 at SLC34A1, rs12539707 at HIBADH, and rs12626330 at CLDN14 were associated with the risk of calcium nephrolithiasis in Chinese Han population." (PMID 35910217, 2022). "Although further investigation is required, we assumed that the polymorphism of WDR72, DGKH, and CLDN14 could increase the risk of calcium nephrolithiasis by influencing the CaSR signaling." (PMID 35910217, 2022).
chronic kidney disease (1 paper, 2024). Impairment of the renal function secondary to chronic kidney damage persisting for three or more months. "In the same study, WDR72-rs77593734 was also associated with eGFRSCysC (P = 1.9E-16) and BUN in UKB participants, confirming previous results in BUN for 416,076 participants from the Chronic Kidney Disease Genetics (CKDGen) Consortium (P = 8.5E-17)." (PMID 38858654, 2024).
colorectal adenocarcinoma (1 paper, 2024). The most common type of colorectal carcinoma. "Subsequently, we selected the NCI-H716 cell line, which exhibits the highest expression of WDR72 among colorectal adenocarcinoma cell lines according to the CCLE database, for WDR72 gene knockdown." (PMID 39268080, 2024).
diabetic retinopathy (1 paper, 2023). "Tryptophan‐aspartate repeat domain 72 (WDR72) is highly expressed in the retina and kidney epithelium, and WDR72 variants were associated with changes in HbA1c in the intensive arm of the DCTT, making this gene a promising biological candidate for the risk of progression of diabetic retinopathy." (PMID 37452207, 2023).
Enamel Renal Syndrome (1 paper, 2025). "Despite the absence of molecular confirmation, the clinical profiles were suggestive of syndromic forms, such as Enamel Renal Syndrome (ERS) and WDR72-related conditions." (PMID 41427162, 2025).
gastric cancer (1 paper, 2025). A primary or metastatic malignant neoplasm involving the stomach. "WDR72 was negatively correlated with activated memory CD4+ T cells and positively associated with resting CD4 memory T cells, consistent with findings in gastric cancer." (PMID 41332473, 2025).
hepatic cirrhosis (1 paper, 2024). "Furthermore, the liver tissues of patients with liver failure and hepatic cirrhosis exhibited downregulated expression of CBS, CYP1A2, FOXA1, GSTZ1, WDR72 and UHMK1 when compared to healthy controls." (PMID 38287425, 2024). "Notably, the expression of FOXA1, GSTZ1, WDR72 and UHMK1 was more upregulated in the tissues of individuals with hepatic cirrhosis than those with liver failure, although statistical significance was not achieved." (PMID 38287425, 2024).
Hypertension (1 paper, 2013). The presence of chronic increased pressure in the systemic arterial system. "The best two-locus model from multivariate GMDR included rs7791839 in CCDC129 gene and rs7168365 in WDR72 implying that the interaction between CCDC129 and WDR72 genes was identified as a significant contributor to the repeatedly measured hypertension status." (PMID 24565370, 2013).